TXNIP (thioredoxin interacting protein)
Diseases named in the same sentence as TXNIP in open-access papers (continued):
Sharing a sentence is not in itself a finding about the gene and the disease.
Hyperglycemia (continued). "Hyperglycemia inhibits thioredoxin ROS-scavenging function through induction of thioredoxin-interacting protein (Txnip), which interacts with thioredoxin and serves as an endogenous inhibitor." (PMID 24834056, 2014). "TXNIP is the endogenous inhibitor of the ROS scavenger thioredoxin (Trx) and contributes to hyperglycemia-induced oxidative stress." (PMID 25165577, 2014). "Recent studies including our own demonstrated that hyperglycemia induces the expression of thioredoxin interacting protein (TXNIP), which in turn promotes RAGE expression and chronic inflammation." (PMID 25165577, 2014). "Recently, it was reported that hyperglycemia-induced oxidative stress was primarily due to the induction of Trx1 inhibitory protein (TXNIP), an endogenous inhibitor of Trx1 activity, leading to the inhibition of the antioxidant function of Trx1." (PMID 22474423, 2012). "The results demonstrate that TXNIP is a glucose-sensitive gene and its expression remains upregulated when hyperglycemia persists." (PMID 22474421, 2012). "Studies are warranted to investigate the role of Trx1 and TXNIP in the induction of ER stress response to hyperglycemia in endothelial cells." (PMID 22474423, 2012). "The results demonstrate that TXNIP mediates, at least in part, cellular oxidative stress, ATP reduction, and an autophagic response in retinal Muller glia under chronic hyperglycemia." (PMID 22474421, 2012). "The observation that the AMPK activators metformin and AICAR markedly decreased TXNIP expression at high glucose further supports the role of AMPK in the regulation of TXNIP under conditions of hyperglycemia." (PMID 22194917, 2011). "We also showed that hyperglycemia-regulated TXNIP-ROS-TRX axis was relevant for the response of MDA-MB-231 cells to paclitaxel cytotoxicity." (PMID 21910912, 2011). "Hyperglycemia [20 mM versus 5 mM glucose] significantly affected the fold-change of increased levels of TXNIP RNA level (mean 1.37 ± 0.17) and ROS level (mean 1.70 ± 0.25) in NCIH9292, ARH77 and U266B1 cells." (PMID 21910912, 2011). "As expected, phloretin blocked the hyperglycemia effect on TXNIP RNA level (1.5 ± 0.05 vs. 1.03 ± 0.03, p < 0.01) and significantly reduced ROS (2.1 ± 0.08 vs 1.84 ± 0.14, p < 0.05) in ARH77 cells." (PMID 21910912, 2011). "Under conditions of hyperglycemia, residual AMPKalpha activity restricts the TXNIP stimulation by glucose." (PMID 22194917, 2011). "The residual activity of AMPK in hyperglycemia restrains TXNIP expression, as its knockdown augmented glucose stimulation of TXNIP." (PMID 22194917, 2011). "We have previously shown that hyperglycemia regulates thioredoxin (TRX) activity-reactive oxygen species (ROS) through induction of thioredoxin-interacting protein (TXNIP) in metastatic breast cancer-derived cells MDA-MB-231." (PMID 21910912, 2011). "In this study, we show that the metabolic condition of hyperglycemia affects the level of both TXNIP RNA and protein in breast-cancer derived cells MDA-MB-231." (PMID 17555594, 2007). "Conclusively, we show that hyperglycemia finely regulates the expression of TXNIP in breast-derived cancer cells MDA-MB-231." (PMID 17555594, 2007). "We show that hyperglycemia by itself has a major impact on both the level of TXNIP and the regulation of ROS level/TRX activity in MDA-MB-231 cells." (PMID 17555594, 2007). "Thioredoxin-interacting protein (TxNIP) was recently established as a novel proapoptotic gene in the β-cells that is significantly overexpressed during hyperglycemia in T1D, and its expression in β-cells is directly elevated due to the toxic effects of continuous exposure to elevated glucose." (PMID 40014914, 2025). "Increased TXNIP expression in mouse spinal cord may induce endothelial cell dysfunction in the case of long-term hyperglycemia." (PMID 41144575, 2025). "In a retinal damage model induced by ischemia/reperfusion or hyperglycemia, TXNIP might influence Müller cell activation by regulating mitochondrial function." (PMID 39736512, 2024).
Hyperglycemia (continued). "Additionally, TXNIP is also a glucose-sensitive gene, and its deletion has been shown to attenuate hyperglycemia-induced endothelial dysfunction and VSMC inflammation during atherogenesis." (PMID 39462409, 2024). "Chronic hyperglycemia results in the suppressed activity of mTOR associated with AMP-activated protein kinase-induced increase in ROS formation and enhanced expression of thioredoxin interacting protein (TXNIP) a potential sensor of glucose and oxidative stress." (PMID 37597078, 2023). "Hyperglycemia activates it by the ATP/P2X purinergic receptor 4 and the induction of TXNIP." (PMID 37762961, 2023). "We speculate that elevated expression of SNHG15 may be compensatory to overexpression of TXNIP in lumbar SC in hyperglycemia." (PMID 37462767, 2023). "Our results suggest that Glo-1 and TXNIP might be partners-in-crime mediating hyperglycemia and the oxidative stress-driven onset and progression of micro- and macrovascular complications in T2DM." (PMID 37759966, 2023). "NLRP3 silencing or thioredoxin interacting protein (TXNIP) silencing blocked these alterations in hyperglycemia-induced RMEC and diabetic rat retinas, indicating that the TXNIP pathway mediates NLRP3 inflammasome activation and that inflammasome activation leads to inflammation in DR." (PMID 35813208, 2022). "Interestingly, most recent study identified a small molecule that inhibit TXNIP expression and ameliorates hyperglycemia in both mice model of T2D (db/db) and T1D (STZ)." (PMID 32824669, 2020). "However, UC-MSCs downregulated the expression of TXNIP induced by hyperglycemia and reduced the following oxidative stress and apoptosis reaction in renal cells, which significantly alleviated nephrocyte injury and improved renal function of DN rats." (PMID 32405507, 2020). "Furthermore, we recently published that hyperglycemia-induced TXNIP upregulation in RPE cells where Trx1 and Trx2 are inhibited causes mitochondrial damage, mitophagic flux to lysosomes and lysosomal enlargement in human RPE cells under diabetic conditions." (PMID 31649499, 2019). "HG levels increase TXNIP expression in both mitochondria and the cytosol and decrease the expression of redox proteins, such as cytosolic Trx1 and mitochondrial Trx2, suggesting that hyperglycemia induces RPE redox stress." (PMID 31023645, 2019). "Interestingly, in a recent study OGA mRNA levels in leucocytes from patients with type 2 diabetes were significantly correlated with TxNIP mRNA levels, as well as with blood markers of hyperglycaemia (HbA1C, Fructosamine)." (PMID 31164864, 2019). "The biological relevance of TXNIP dysfunction may be particularly relevant in cases of recurrent hyperglycemia." (PMID 31835423, 2019). "Similarly, hyperglycemia-induced TXNIP can activate p38 and Erk1/2 MAPK pathways in pancreatic cancer model and TXNIP expression is positively correlated with poor prognosis in pancreatic cancer patients." (PMID 30627326, 2018). "One possibility is that during chronic hyperglycemia, sustained TXNIP expression and ROS/RNS stress prevail under mitochondrial damage, which may cause a reduction of the delipidating activity of ATG4B on LC3BII." (PMID 28492550, 2017). "Furthermore, gene silencing of TXNIP reduced hyperglycaemia-elevated ROS production and apoptosis in cardiomyocytes within H/R." (PMID 27867451, 2016). "Hyperglycaemia has been identified as an inducer of TXNIP expression in various cells including HK-2; meanwhile, enhanced myocardial TXNIP expression that contributes to hyperglycaemia-aggravated oxidative stress and exacerbates cardiac injury following I/R has been reported." (PMID 27867451, 2016). "Thus we concluded that under hyperglycemia TXNIP accumulation was an upstream event for the following NADPH oxidase (gp91phox) activation in podocytes." (PMID 25834832, 2015). "Also, hyperglycemia regulates thioredoxin-ROS activity through induction of TXNIP in breast cancer derived cells." (PMID 25605021, 2015).
Hyperglycemia (continued). "Even in the presence of hyperglycemia, inhibition of TXNIP expression prevents both epigenetic alterations and DR progression, suggesting that TXNIP may play a key role in establishment and maintenance of the metabolic memory." (PMID 25165577, 2014). "TXNIP is early induced by hyperglycemia in vitro and diabetes in vivo diabetic retina." (PMID 25165577, 2014). "In addition, hyperglycemia leads to the binding of the histone acetyltransferase p300 to the promoter of TXNIP in the retina of diabetic animals." (PMID 25165577, 2014). "Secondly, we show that chronic hyperglycemia sustains TXNIP up-regulation in Muller glia in in vitro culture and orchestrates a temporal program of innate host defense mechanisms that lead to cellular oxidative stress, ER stress, inflammation, and autophagy/apoptosis." (PMID 22474421, 2012). "To assess whether p38 MAP kinase signaling pathway affected hyperglycemia-regulated TXNIP/TRX/ROS axis, we treated MDA-MB-231 cells with 20 μM of the specific kinase inhibitor SB203580." (PMID 17555594, 2007). "Furthermore, hyperglycemia has also been shown to promote oxidative stress through inhibition of TRX function by TXNIP in human aortic smooth muscle cells (ASMCs)." (PMID 17555594, 2007). "TXNIP levels are reported to be elevated in diabetic patients and under hyperglycemia, suggestive of the fact that TXNIP not only regulates the onset of diabetic vascular complications due to its involvement in hyperglycemia and oxidative stress, but also plays a role in their progression." (PMID 37759966, 2023). "However, under sustained hyperglycemia and DR, TXNIP expression, redox stress, and mitochondrial dysfunction may occur." (PMID 34940029, 2021). "Interestingly, genetic deletion or mutation of TXNIP in diabetic model mice such as ob/ob mice, STZ-induced diabetic mice and HFD mice exhibited improved glucose tolerance and remission of hyperglycemia." (PMID 32824669, 2020). "TXNIP is a nucleoprotein which could be significantly upregulated by hyperglycemia." (PMID 32405507, 2020). "However, there is no direct evidence to support a causative role of TXNIP in hyperglycemia or high blood glucose which exasperates renal I/R injury." (PMID 27867451, 2016). "Therefore, TXNIP may be induced via hyperglycemia regulated thioredoxin-ROS activity in Her-1/2 signaling pathway." (PMID 25605021, 2015). "Indeed, hyperglycemia has been shown to increase TXNIP in adipocytes, and enhance inflammation in adipose tissue, which in turn may adversely affect glucose metabolism." (PMID 23691179, 2013). "Thus, a temporal and spatial survival response of Muller cells to chronic hyperglycemia emerges and TXNIP may orchestrate some of these events." (PMID 22474421, 2012). "Hyperglycemia potently activates the NLRP3 inflammasome by elevating reactive oxygen species (ROS) production, which upregulates thioredoxin-interacting protein (TXNIP)." (PMID 41601761, 2026). "Therefore, a calcium blockade by pharmaceutical intervention can effectively target not 1, but several β-cell fragilities associated with hyperglycemia-induced metabolic stress through the downregulation of proapoptotic factor TxNIP and reduce extracellular proapoptotic signaling via IGFBP3." (PMID 40014914, 2025). "Metformin-activated AMPK directly hinders hyperglycemia-stimulated nuclear translocation of ChREBP and forkhead box O1 (FOXO1), preventing their subsequent recruitment on TxNIP promoter." (PMID 40014914, 2025). "Increased TXNIP synergizes with activation of the UPR, also activated in hyperglycemia, to stimulate inflammatory signaling via the NLRP3 inflammasome." (PMID 38292764, 2023). "Hyperglycemia activates the NLRP3 inflammasome, accompanied by TXNIP activation, which inhibits the expression of thioredoxin." (PMID 33637069, 2021).
Hyperglycemia (continued). "Several previous studies had established a prominent role for TXNIP in mediating retinal NLRP3-inflammasome activation in other models of type-1 diabetes, hyperglycemia and retinal neurotoxicity." (PMID 32492941, 2020). "TXNIP knockout by CRISPR and TXNIP gRNA or by siTXNIP prevents hyperglycemia-induced mitochondrial damage, ATP reduction, and excess mitophagic flux in Müller glial cells and RPE." (PMID 33302369, 2020). "TXNIP deletion improves GSIS function in the T2D model ob/ob mice, which contributes the amelioration of hyperglycemia." (PMID 32824669, 2020). "In T2DM, hyperglycemia can lead to oxidative stress via increased NADPH oxidase activity, overproduction of mitochondrial ROS and elevated expression of TXNIP." (PMID 32508651, 2020). "This view is supported by the finding that chronic hyperglycemia induced the upregulation of the oxidative sensor and NLRP3 modulator TXNIP, with consequent activation of inflammatory signaling pathways in both glial and microvascular endothelial cells." (PMID 32751658, 2020). "Recent work demonstrated that TXNIP induced NLRP3 expression, activation of caspase-1, and release of IL-1β in a model of hyperhomocysteinemia or hyperglycemia with podocyte injury." (PMID 27867451, 2016). "In conclusion, we demonstrated that TRPM2 was a Ca2+ mediator of hyperglycemia-induced ROS production and NLRP3 inflammasome activation through cooperatively interaction with p47 phox, and regulation of TXNIP in human monocytes." (PMID 27731349, 2016). "We assessed the TXNIP RNA level, ROS production and TRX activity in response to isolated hyperglycemia." (PMID 21910912, 2011). "Hyperglycemia in GDM leads to reduced expression levels of miR-17-5p, upregulation of its target gene TXNIP, and subsequent activation of NLRP3 inflammasome, ultimately leading to the release of inflammatory cytokines and contributing to impaired trophoblast glucose uptake." (PMID 40559375, 2025). "Recent investigations have underscored that hyperglycemia stimulates inflammatory factors to activate microglial NLRP3 in hippocamp, upregulating P2X7R and enhancing ROS production and TXNIP expression, all of which likely mediate the emergence of depression in diabetic mice model." (PMID 38916735, 2024). "Specifically, under sustained hyperglycemia in DM, HG leads to the overproduction of reactive oxygen species (ROS) leading to thioredoxin (TRX)-interacting protein (TXNIP) to dissociate from TRX, enhancing TXNIP expression and activation of the NLRP3 inflammasome." (PMID 33981238, 2021). "Hyperglycemia-induced ROS production may stimulate NLRP3 inflammasome activity through different pathways, including thioredoxin (TRX1)-TXNIP dissociation and accumulation of AGEs and advanced lipoxidation endproducts (ALEs)." (PMID 32751658, 2020). "In this study, the protein level of inflammasome components, NLRP3 and ASC, was not affected by Exendin-4-treated hyperglycemia cultured cardiomyocytes, while the upstream activator of inflammasome, TXNIP, was downregulated significantly." (PMID 31886288, 2019). "We first evaluated TxNIP expression and O-GlcNAcylation in islets of GK rats, a diabetic but non-obese rat model with moderate hyperglycemia but severe β cell defect." (PMID 31164864, 2019). "The thioredoxin-interacting protein, TXNIP, is induced in vivo by hyperglycemia and it inhibits the antioxidative function of thioredoxin resulting in accumulation of reactive oxygen species, cellular stress, and induction of the miR-200 family which induces apoptosis through inhibition of ZEB1." (PMID 31683538, 2019). "Thioredoxin-interacting protein (TXNIP), a redox signaling regulator, is upregulated significantly in response to hyperglycemia and is reported to be a direct ligand of the NLRP3 inflammasome, at least in some contexts, although conflicting observations have been reported." (PMID 29515457, 2018).
Hyperglycemia (continued). "TXNIP is a member of the alpha arrestin protein family that regulates and binds to reduced thioredoxin (TXN) and can be induced in response to oxidative stress, calcium influx and hyperglycemia." (PMID 30670947, 2018). "Our hyperglycemia experiments showed very high expression of thioredoxin interacting protein (TXNIP) in microarray results (data not shown)." (PMID 25193495, 2014). "We found that the regulation of TXNIP gene expression by glucose in MDA-MB-231 cells occurs rapidly within 6 h of its increased level (20 mM glucose) and persists through the duration of the conditions of hyperglycemia." (PMID 17555594, 2007). "In cases of hyperglycemia, following G6P-promoted allosteric conformational changes, both MFPs translocate to the nucleus and independently bind the MLX transcription factor, activating the expression of genes via the ChoRE element within the promoters of target genes, such as TXNIP." (PMID 39851533, 2025). "In fact, chronic hyperglycemia may induce the secretion of IL-Ι β via the activation of the NLRP3 inflammasome facilitated by the production of ROS and thioredoxin-interacting protein (TXNIP)." (PMID 38916735, 2024). "In another study, KMT6A downregulated TxnIP expression through H3K27me3 enrichment in the promoter region of the transcription factor paired box 6 (Pax6), whereas the depletion of KMT6A led to an increase in the hyperglycemia-induced reactive oxygen species (ROS) levels and cellular death." (PMID 36983082, 2023). "Both high hyperglycemia and lipopolysaccharide levels may activate the NLRP3 inflammasome in mesangial cells through the reactive oxygen species (ROS)/thioredoxin-interacting protein (TXNIP) pathway." (PMID 37197354, 2023). "However, in the current exploratory study, we did not address the ultimate effect of hyperglycemia-mediated TXNIP expression on apoptosis." (PMID 17555594, 2007). "On the other hand, hyperglycemia seems to have a protective effect by increasing TRX activity and reducing ROS level in MC/CAR cells, the ones not responding to glucose-TXNIP regulation." (PMID 21910912, 2011).